CCL24 (C-C motif chemokine ligand 24)
Diseases named in the same sentence as CCL24 in open-access papers (continued):
Sharing a sentence is not in itself a finding about the gene and the disease.
colorectal cancer (9 papers, 2016 to 2026). A primary or metastatic malignant neoplasm that affects the colon or rectum. "In the context of cancer, CCL24 expression has been shown to associate with poor prognosis in colorectal cancer and also contribute to hepatocellular carcinoma malignancy via the RhoB-VEGFA-VEGFR2 angiogenesis pathway." (PMID 31649887, 2019). "A chemokine panel was used to screen plasma samples from patients with colorectal cancer, and five chemokines and four cytokines identified as associated with increased total mortality, among which TNF-α and CCL24 were exclusively associated with colorectal cancer-specific mortality." (PMID 31836011, 2019). "This study investigates the role of C-C motif chemokine ligand 24 (CCL24) in immune regulation in colorectal cancer (CRC)." (PMID 41694595, 2026). "CCL24 is one chemotactic factor extensively studied in airway inflammation and colorectal cancer but less studied in hepatocellular carcinoma (HCC) retrospectively." (PMID 28042950, 2017). "Meanwhile, via up-regulating CCL24 stimulated by Th2 cell factors, the immune microenvironment was more suitable for colorectal cancer cells to plant or/and progress." (PMID 28042950, 2017). "The elevated level of CCL24 was found in primary colorectal cancer biopsies." (PMID 27723802, 2016). "Some authors reported that colorectal cancer could have eosinophilic infiltration, and that colorectal cancer had the potential for expression of various chemokines, such as interleukin (IL)-2, IL-3, IL-5, CCL (CC chemokine ligand) 11, or CCL24, that trigger eosinophil development and migration." (PMID 33109117, 2020).
hepatocellular carcinoma (8 papers, 2017 to 2024). A malignant tumor that arises from hepatocytes. "A recent study also demonstrated that CCL24 contributes to hepatocellular carcinoma malignancy through RhoB-VEGFA-VEGFR2 and indicates poor prognosis." (PMID 32051393, 2020). "CCL24, a member of the CC class of chemokines, has been shown to play a protumoral role in several malignant tumors, such as hepatocellular carcinoma and colon cancer." (PMID 32051393, 2020). "In liver diseases such as non-alcoholic steatohepatitis (NASH) and hepatocellular carcinoma (HCC), CCL24 and CCR3 are upregulated, and CCL24 blockade with the neutralizing antibody CM-101 reduced liver damage and fibrosis in preclinical models." (PMID 38334601, 2024). "In hepatocellular carcinoma (HCC) cells, CCL24, a chemotactic factor, was shown to promote migration and invasion via a RhoB-VEGFA signaling pathway." (PMID 29385717, 2018).
allergic asthma (7 papers, 2007 to 2026). A asthma with a basis in a pathological type I hypersensitivity reaction. "At present, there is consensus that M2a cell is elicited by IL-4- and IL-13 and secret high levels of IL-13 and chemokines, including TARC and CCL24, that activate Th2 immunity and promotes eosinophil trafficking, which induces allergic asthma." (PMID 36175886, 2022). "Ccl24 (eotaxin 2) plays a role in eosinophil recruitment to the lung in allergic asthma." (PMID 18087596, 2007). "Hallmark features of type 2 human allergic asthma are circulating, airway, and tissue eosinophils accompanied by elevated TH2 lymphocytes, suggesting a mechanistic link between elevated DC expression of Ccl24, observed in this study, and elevated airway eosinophilia and type 2 immune responses." (PMID 27484038, 2017).
liver fibrosis (7 papers, 2011 to 2025). "CCL24 serum levels correlated with Enhanced Liver Fibrosis score, most notably in patients with high alkaline phosphatase levels." (PMID 37345655, 2023). "Similarly, ANIT and BDL models showed reduced liver fibrosis and reduced biliary hyperplasia following CCL24 blockade." (PMID 39851534, 2025). "Blocking CCL24 with i.v. twice-weekly injection of 10 mg/kg CM-101 (D8) reduced biliary damage, as observed by reduced cholangiocyte proliferation (pan-CK staining) and reduced liver fibrosis (SR staining)." (PMID 37345655, 2023). "Additionally, in several animal models of NASH and liver fibrosis, CCL24 blockage by the anti-CCL24 monoclonal antibody, CM-101 (D8), significantly reduces liver damage, most importantly by directly reducing liver fibrosis." (PMID 37345655, 2023). "Also, the blockade of CCL24 using a monoclonal antibody robustly attenuated liver fibrosis and inflammation in animal models, thus suggesting a potential therapeutic role for an anti-CCL24 agent." (PMID 32545403, 2020). "However, individual chemokine concentrations, such as CCL3, CCL7, CCL24 (eotaxin-2), Macrophage Migration Inhibitory Factor (MIF), and soluble TNF-α receptor 1, were positively associated with Schistosoma-related liver fibrosis." (PMID 30619332, 2018). "Blocking CCL24 was shown to reduce liver damage in various experimental animal models of MASH, including the methionine-choline-deficient (MCD) diet-induced and streptozotocin-high-fat-diet (STAM)-induced MASH models, and the thioacetamide (TAA)-induced liver fibrosis model." (PMID 39851534, 2025). "To better understand the relationship between CCL24 expression and progressive fibrosis in PSC, we correlated serum CCL24 levels with the validated Enhanced Liver Fibrosis (ELF) score." (PMID 37345655, 2023). "Interestingly, a humanized CCL24-neutralizing monoclonal antibody, CM101, was shown to significantly mitigate liver fibrosis and inflammation in preclinical models of NASH and primary sclerosing cholangitis." (PMID 40492139, 2025). "Emerging evidences showed that CCL24 was elevated in the blood and liver of patients with NASH and primary sclerosing cholangitis, the levels of CCL24 were positively correlated with enhanced liver fibrosis scores." (PMID 40492139, 2025). "CCL24 has many properties comparable with CCL11, and may be able to promote granuloma formation and hepatic fibrosis via a similar mechanism." (PMID 21666794, 2011).
lung fibrosis (7 papers, 2021 to 2025). "In several independent studies, CCL24 was shown to be upregulated and associated with disease severity in patients with idiopathic pulmonary fibrosis and systemic sclerosis." (PMID 37345655, 2023). "Notably, as suggested by our cytokine antibody arrays, levels of CCL24 (also known as eotaxin-2), a chemokine strongly associated with dermal and pulmonary fibrosis, were lower in Piezo1 knockdown HDFs grown on higher substrate stiffness." (PMID 38267432, 2024). "Using bleomycin-induced models of dermal and pulmonary fibrosis, CCL24 knockout prevented dermal thickening, reduced collagen content, and reduced white blood cell and mononuclear cell counts in bronchoalveolar lavage (BAL) fluid." (PMID 39851534, 2025). "As a type 2 cytokine, CCL24 was found to participate in the development of various diseases, amongst which are primary biliary cirrhosis, idiopathic pulmonary fibrosis, rheumatoid arthritis, atherosclerosis, asthma, as well as in malignancies." (PMID 39851534, 2025). "Results of BALF proteomics from IPF samples show an up-regulation of CCL24, suggesting the role of this chemokine as a mediator of pulmonary fibrosis." (PMID 39768150, 2024). "CCL24 has been shown to promote collagen production in human lung fibroblasts and plays a critical role in promoting profibrotic effects in idiopathic pulmonary fibrosis (IPF)." (PMID 38267432, 2024). "In bleomycin-induced experimental animal models, the blockade of CCL24 with CM-101 profoundly inhibited pulmonary fibrosis and inflammation." (PMID 39768150, 2024). "The results of the study, in which the main aim was to assess the ability of CCL24-blocking antibody CM-101 to interfere with profibrotic activities induced by CCL24, in both in vitro and in vivo models of skin and lung fibrosis, are promising." (PMID 35268401, 2022). "The implication of eotaxins in lung fibrosis are poorly understood, nonetheless, CCL11 is increased in experimental lung fibrosis while CCL11 deficient mice are protected and both CCL11, CCL24 and CCL26 are able to influence fibroblast behavior." (PMID 34093523, 2021).
allergic rhinitis (6 papers, 2019 to 2025). Inflammation of the nasal mucous membranes caused by an IgE-mediated response to external allergens. "In contrast, an increased ability of isolated HDL derived from allergic rhinitis patients to suppress eosinophil effector responses upon eotaxin-2/CCL24 stimulation was demonstrated." (PMID 34064071, 2021). "Of particular interest, HDL that was derived from allergic rhinitis patients showed an improved ability to suppress eosinophil effector responses upon eotaxin-2/CCL24 stimulation." (PMID 33271807, 2020). "For eotaxin chemokines, CCL11 and CCL24 levels were increased in asthma and allergic rhinitis, and CCL26 levels were increased in allergic rhinitis and atopic skin inflammation." (PMID 33317619, 2020).
atopic dermatitis (6 papers, 2020 to 2025). "We examined messenger ribonucleic acid (mRNA) expression levels of IL-8 as a neutrophil-related marker and eotaxin-2/CCL24 as an eosinophil-related marker for DIOSD in patients with atopic dermatitis undergoing treatment with dupilumab." (PMID 36184619, 2022). "By contrast, atopic dermatitis and Th2-related genes, including Il4, Il5, Il13 and Il31 were lowly expressed or not detected at all, and other atopic dermatitis-related transcripts (Ccr4, Ccl17, Ccl24) were not significantly differentially expressed." (PMID 38528069, 2024). "Eosinophils were stimulated with eotaxin-2/CCL24 in the presence or absence of HDL (isolated from patients suffering from atopic dermatitis and healthy controls) and morphological changes (evaluated by the change in shape via flow cytometry) or chemotaxis was monitored." (PMID 33271807, 2020).
fibrosis (6 papers, 2016 to 2025). the formation of excess fibrous connective tissue in an organ or tissue in a reparative or reactive process. "CCL24 blockade ameliorated liver condition, evidenced by reduced liver fibrosis, biliary hyperplasia, and liver necrosis." (PMID 38334601, 2024). "CCL24 was previously verified to participate directly in the process of skin, pulmonary, and liver inflammation and fibrosis in humans." (PMID 36131165, 2023). "There was a significant decrease in cardiac fibrosis in CCL24 Ab–treated animals compared with Ang II–induced mice according to both Masson stain and Sirius red stain in the same area of heart sections." (PMID 36131165, 2023). "Higher levels of CCL24 and CCR3 were found in the skin and sera of patients with SSc compared with healthy controls; elevated levels of CCL24 and CCR3 were associated with fibrosis and predictive of greater lung function deterioration." (PMID 37555717, 2023). "Previous studies have shown that both CCL24 and CCR3 are involved in skin and lung inflammation and fibrosis." (PMID 38267432, 2024). "Similarly, blocking CCL24 using a monoclonal antibody reduced collagen content and white blood cell counts in BAL fluid in the bleomycin-induced pulmonary fibrosis model, reinforcing a role for the CCL24-CCR3 axis in dermal and pulmonary inflammation, fibrosis, and vasculopathy." (PMID 39851534, 2025).
systemic sclerosis (6 papers, 2022 to 2025). A chronic disorder, possibly autoimmune, marked by excessive production of collagen which results in hardening and thickening of body tissues. "Moreover, blocking CCL24 with an anti-CCL24 monoclonal antibody in a systemic sclerosis preclinical model resulted in reduction of both skin and lung inflammation and fibrosis." (PMID 37345655, 2023). "CCL24 plays an important role in the pathological processes of skin and lung inflammation and fibrosis, and its antibody treatment can potentially be beneficial for therapeutic use in systemic sclerosis." (PMID 36755348, 2023). "Higher levels of CCL24 and CCR3 were found in the tissue and sera of patients with fibro-inflammatory diseases, including primary sclerosing cholangitis (PSC), systemic sclerosis (SSc), and metabolic dysfunction-associated steatohepatitis (MASH)." (PMID 39851534, 2025).
primary sclerosing cholangitis (5 papers, 2023 to 2025). "To corroborate these CCL24-dependent inflammatory modifications, we examined the Mdr2−/− mice model for sclerosing cholangitis." (PMID 38334601, 2024). "We studied the role of CCL24 in primary sclerosing cholangitis (PSC) and evaluated the potential therapeutic effect of blocking CCL24 in this disease." (PMID 37345655, 2023).
fibromyalgia (4 papers, 2018 to 2022). A chronic disorder of unknown etiology characterized by pain, stiffness, and tenderness in the muscles of neck, shoulders, back, hips, arms, and legs. "Increased serum or CSF CCL24 levels have been reported in patients with fibromyalgia syndrome, neurodegenerative diseases, Huntington's disease,25Listeria monocytogenes meningitis, neuromyelitis optica, and secondary progressive multiple sclerosis." (PMID 32419252, 2020).
melanoma (4 papers, 2017 to 2023). A malignant, usually aggressive tumor composed of atypical, neoplastic melanocytes. "Moreover, alveolar macrophages performed significant enhancement of M2 functions, especially CCL24 secretion, in the Abt mice challenged with B16/F10 melanoma." (PMID 28785009, 2017). "When the normal alveolar macrophages were transferred or the higher levels of CCL24 were neutralized, the frequency and number of γδT cells, particularly IL-17A + γδT cells, significantly increased in the lungs of the Abt mice after challenged with B16/F10 melanoma cells." (PMID 28785009, 2017). "In studies using neuroblastoma and melanoma murine models, the absence of CD200/CD200R signaling (using CD200R- mice) caused TAMCs to upregulate CCL24 and CCL8 levels but downregulate the production of CXCL3, CXCL2, and CCL3." (PMID 38137547, 2023). "We next assessed whether IL-33 induced the expression of eosinophil-attracting chemokines (CCL11, CCL24, CCL26, and CCL5) in melanoma cells and found significant up-regulation of CCL5 and CCL24." (PMID 31717819, 2019). "Thus, the production of CCL24 and CCL8, and the reduction of CXCL3, CXCL2, and CCL3 in TAMCs, explain why mice lacking intact CD200/CD200R signaling more potently rejected neuroblastoma and melanoma tumors relative to wild-type conditions." (PMID 38137547, 2023).
osteosarcoma (4 papers, 2019 to 2023). A usually aggressive malignant bone-forming mesenchymal neoplasm, predominantly affecting adolescents and young adults. "Melatonin attenuates chemokine CCL24 levels through inhibition of the JNK pathway to hinder human osteosarcoma cell invasion." (PMID 37197432, 2023). "The manipulation of CCL24 levels affects osteosarcoma cells motility, invasion, and migration." (PMID 31798348, 2019). "While melatonin, up to 2.0 mM, has no cytotoxic effects, it intriguingly suppresses cellular motility, migration, and invasion in human osteosarcoma U2OS and HOS cells and represses the gene expression of C-C motif chemokine ligand 24 (CCL24) in U2OS cells." (PMID 31842295, 2019). "Altogether, U2OS and HOS cell-derived CCL24 contributes to cellular invasion and migration through the upstream JNK signaling pathway; this finding implies a promotional role of CCL24 in osteosarcoma metastasis; the action is inhibited by melatonin." (PMID 31842295, 2019). "Authors documented that melatonin was decreased the level of chemokine CCL24 via inhibition of the JNK pathway and subsequently preventing osteosarcoma invasion." (PMID 31798348, 2019). "This study provides the clinical insight that chemokine signaling pathway genes (CCL21, CCL22, CCL24, CXCL11, CXCL12, CXCL13, GNAI2, and RAC2) in proliferating cells might be the potential biomarkers for treatment of osteosarcoma." (PMID 37537613, 2023).
sarcoidosis (4 papers, 2016 to 2025). Sarcoidosis is a multisystemic disorder of unknown cause characterized by the formation of immune granulomas in involved organs. "Meguro reported that, in Japanese and Czech populations, the OR of the rs4728493 risk allele at the CCL24 locus decreases with the progression of the sarcoidosis chest X-ray (CXR) when compared in the CXR stage 0 + I, stage II, and stage III + IV subgroups." (PMID 33912164, 2021). "Our study revealed substantial differences in the allele distribution of numerous SNPs between Asian Japanese and Caucasian Czech controls, even for the CCL24 lead SNP associated with sarcoidosis." (PMID 32826979, 2020). "Of these three loci, C1orf141-IL23R had been previously reported as a sarcoidosis-related locus; however, CCL24 and STYXL1-SRRM3 represented novel susceptibility loci for sarcoidosis." (PMID 32826979, 2020). "We identified three loci outside the HLA complex, CCL24, STYXL1-SRRM3, and C1orf141-IL23R, which showed genome-wide significant associations (P < 5.0 × 10−8) with sarcoidosis; CCL24 and STYXL1-SRRM3 were novel." (PMID 32826979, 2020). "The current study was the first to describe an association between CCL24 variants and sarcoidosis." (PMID 32826979, 2020). "CCL24 is an eotaxin, which is upregulated by Th2-biased immune responses; thus, these findings indicate that Th1 polarization associated with decreased expression of CCL24 might be important in onset and maintenance of the early stage and acute subtype of sarcoidosis." (PMID 33912164, 2021). "The highest OR was observed for susceptible SNPs in both CCL24 and STYXL1-SRRM3 in the acute systemic Lofgren’s syndrome compared with sarcoidosis with any chest X-ray stage in the Czech population." (PMID 33912164, 2021). "Among those, CCDC88B and ANXA11 are potential regulators of apoptosis, whereas CCL24 was increased in broncho-alveolar lavage (BAL) of patients with stage 3 sarcoidosis compared to patients with Lo ̈ fgren syndrome and IL23R has been implicated in the formation of granulomas." (PMID 41466414, 2025). "Our findings suggest that genetic control, through genetic polymorphisms in CCL24, POR, and IL23R, may have an important physiological role in the development and progression of sarcoidosis." (PMID 32826979, 2020). "Indeed, after conditioning on rs4728493, we found that rs112463197 and rs112680895 were associated with sarcoidosis, independent of CCL24 variants (PGC = 8.7 × 10−11 across all three cohorts)." (PMID 32826979, 2020). "We speculate that the CCL24 risk allele might be involved in a polarized Th1 response in sarcoidosis, and that POR and IL23R risk alleles may lead to diminished host defense against sarcoidosis pathogens." (PMID 32826979, 2020). "Overall, SNPs from the following genes have already been identified in previous studies on sarcoidosis (GWAS or other): CCDC88B, ANXA11, IL23R, FAM117B, CCL24, ATXN2/SH2B3." (PMID 41466414, 2025). "Several proteins were identified with higher abundance in BAL of sarcoidosis patients, including cadherin 5 (CDH5), transferrin (TF), C-C motif chemokine 24 (CCL24), interleukin 15 (IL15) apolipoprotein A (LPA) and mitochondrial superoxide dismutase (SOD2)." (PMID 27259755, 2016). "We found three genome-wide significant non-HLA loci, CCL24, STYXL1-SRRM3, and C1orf141-IL23R, that conferred susceptibility to sarcoidosis." (PMID 32826979, 2020). "Our analysis identifies three non-HLA susceptibility loci (CCL24, STYXL1-SRRM3, and C1orf141-IL23R) for sarcoidosis and demonstrates the importance of genetic control of CCL24, POR, and IL23R, through genetic polymorphisms, in the pathogenesis of sarcoidosis." (PMID 32826979, 2020).
colon cancer (3 papers, 2020 to 2023). "CCL24 (Eotaxin-2) has shown promise as a biomarker in multiple cancer types, including colon cancer, non-small-cell cancer, and nasopharyngeal carcinoma." (PMID 38275392, 2023).
malaria (3 papers, 2022 to 2023). Malaria is a serious and sometimes fatal disease caused by a parasite that commonly infects a certain type of mosquito which feeds on humans. "In pregnancy-associated malaria, chemokines such as CXCL-4, CXCL-13, CXCL-16, and CCL-24 play critical roles in leucocyte trafficking to tissue sites in the infected placenta where inflammatory reactions are active." (PMID 36689438, 2023).